LINC02860 (long independently transcribed non-coding RNA 2860)
Synonyms: C7orf71
Gene: Long non-coding RNA gene on chromosome 7 (26,637,865 to 26,647,305, forward strand). Ensembl gene ENSG00000222004.
Diseases named in the same sentence as LINC02860 in open-access papers:
LINC02860 is named in the same sentence as 1 disease in open-access papers, as found by Europe PMC text mining. Sharing a sentence is not in itself a finding about the gene and the disease.
LINC02860 shares sentences with these, for which no sentence is quoted: metastatic melanoma (1 paper).